FOXP3 (forkhead box P3)
Diseases named in the same sentence as FOXP3 in open-access papers (continued):
Sharing a sentence is not in itself a finding about the gene and the disease.
pancreatic cancer (continued). "LSM technology applied to the whole pancreatic tumors allowed us to observe some of Foxp3+ Treg cells to directly contact Gr-1+ cells." (PMID 32038621, 2019). "Cancer-Foxp3 causes immunosuppression by inducing Treg accumulation via CCL5 and negatively correlates with a poor prognosis in pancreatic cancer." (PMID 30060755, 2018). "In pancreatic cancer patients, FoxP3+IL-10+TGF-β+ TI Tregs comprised 12% of the ENO1-specific CD4+ T cell population and specifically inhibited the proliferation of autologous ENO1-specific Teff." (PMID 27509527, 2016). "In hepatocellular carcinoma (HCC) and pancreatic cancer patients, two distinct FoxP3+/− TI Treg subsets exhibiting differential expression patterns of CTLA-4, PD-1, CD25 and CD69 were identified in tumor-infiltrating lymphocyte (TIL) populations." (PMID 27509527, 2016). "Second, FOXP3, the master transcription factor for Tregs, and its effective cytokine IL10, were associated with PDL1 upregulation in pancreatic cancers." (PMID 27589570, 2016). "In this study, we evaluated the distribution of FOXP3+ putative Treg in pancreatic cancer primary tumors and draining lymph nodes, and determined its correlation with critical clinicopathological features." (PMID 25191901, 2014). "In that study, we also used flow cytometry to confirm that the FOXP3+ cells were also CD3+CD4+CD25+CD127−, thus strengthening the suggestion that FOXP3 can serve as a useful marker for Treg in pancreatic cancer." (PMID 25191901, 2014). "In the univariate analysis, both the lymph node status and the density of FOXP3+ lymphocytes in the tumors correlated with the prognosis of the pancreatic cancer patients following radical resection." (PMID 25191901, 2014). "FOXP3+ lymphocyte density in primary pancreatic cancer tissue and draining lymph nodes was measured using immunohistochemistry." (PMID 25191901, 2014). "In our study, univariate analysis demonstrated that the lymph node status and local tumor FOXP3+ lymphocytes density were prognostic factors of pancreatic cancer in patients after radical resection." (PMID 25191901, 2014). "FOXP3+ lymphocyte density in primary tumor tissue in patients with pancreatic cancer correlates with lymph node metastasis." (PMID 25191901, 2014). "In conclusion, we confirmed that the accumulation of FOXP3+ lymphocytes in the primary tumor tissue correlates with lymph node metastasis in pancreatic cancer." (PMID 25191901, 2014). "We recently confirmed that pancreatic cancer is infiltrated by FOXP3+ putative Treg, and this served as a potential explanation for the poor survival of patients despite the high prevalence of CD8+ T cells." (PMID 25191901, 2014). "Consistent with prior studies, we found that the density of FOXP3+ lymphocytes in pancreatic cancer correlated significantly with the histologic grade of the tumor, regardless of the patients' age, gender, tumor size, or local invasion." (PMID 25191901, 2014). "FOXP3+ lymphocyte density in pancreatic cancer was significantly higher than in paratumoral pancreatic tissue." (PMID 25191901, 2014). "The density of FOXP3+ lymphocytes in pancreatic cancer was significantly higher than that in paratumoral pancreatic tissue (4.8±5.2/HP vs. 0.47±0.94/HP, p<0.001)." (PMID 25191901, 2014). "Pancreatic tumors in TNFR1 deficient mice displayed increased vascular density, enhanced infiltration of CD4+ T cells and CD4+ forkhead box P3 (FoxP3)+ regulatory T cells (Treg) but reduced numbers of CD8+ T cells." (PMID 24098720, 2013). "Normal pancreatic ducts cells are devoid of FOXP3 expression, which has been detected in human pancreatic cancer cells." (PMID 23888189, 2012). "In particular, multivariate analysis in pancreatic cancer showed that the prevalence of Foxp3+ T regs was an independent prognostic factor." (PMID 18087278, 2008).
pancreatic cancer (continued). "Limited evidence indicates that it is also expressed, albeit to a lesser extent, in tissues other than thymus and spleen, while, very recently, it was shown that Foxp3 is expressed by pancreatic carcinoma." (PMID 18430198, 2008). "Previous studies have highlighted a role of Foxp3+ Treg cells in regulating tumor immunity, with increased levels of Treg cells observed among tumor-infiltrating lymphocytes in non-small cell lung, ovarian, breast, and pancreatic cancers." (PMID 40297156, 2025). "This suggests that the number of c-FOXP3+ cells could serve as a marker to assess therapeutic efficacy in pancreatic cancer." (PMID 38047300, 2024). "Interestingly, although CD4-positive T cell ablation enables CD8-positive T cell-mediated deterioration of pancreatic tumors in mice, consumption of FOXP3-positive Tregs accelerates tumorigenesis as a result of compensatory myeloid infiltration." (PMID 38352864, 2024). "The most prevalent type of pancreatic cancer is pancreatic ductal adenocarcinoma (PDAC), and an increase in Foxp3 in the tumor microenvironment of pancreatic cancer affects immune cells (DCs), which are antigen-presenting cells, impairing the body’s ability to mount an immune defense." (PMID 38919615, 2024). "In addition, data from TCGA demonstrated that CCL5 expression positively correlated with FOXP3 expression in pancreatic cancer." (PMID 37291128, 2023). "At the same time, this study showed that normal pancreatic ductal epithelial cells do not express FOXP3, suggesting that the interaction between FOXP3 + tumor cells and FOXP3 + positive Treg cells may promote the development of pancreatic cancer." (PMID 36550816, 2022). "In addition, IHC staining showed that 24 of the 39 pancreatic cancer patients showed high expression of tumor FOXP3, and these FOXP3 staining was mostly localized in the cytoplasm, while only a few samples were localized in the nucleus." (PMID 36550816, 2022). "Additionally, Foxp3 serum level indirectly correlates with cachexia severity only in the pancreatic cancer patients." (PMID 34900737, 2021). "Additionally, JTT increases the regulatory activities of T cells by decreasing the forkhead box p3 (Foxp3)+ regulatory T cell (Treg) population in patients with advanced pancreatic cancer." (PMID 34589133, 2021). "Moreover, there is a significant correlation among SOCS1 and Foxp3 protein in cachectic patients with pancreatic cancer." (PMID 34900737, 2021). "Additionally, in a murine model of pancreatic cancer, depletion of FOXP3 expressing cells led to rapid disease progression when compared to mice with FOXP3 expressing cells." (PMID 34638488, 2021). "In the present study, the relationship between FOXP3+ Tregs and lymph node metastasis and distant metastasis in 63 patients with pancreatic cancer was analyzed and a significant correlation with survival time, lymph node metastasis, and distant metastasis was observed." (PMID 33062072, 2020). "Results from a heterotopic mouse model of PDAC using nonmetastatic murine Pan02 cancer cells and an orthotopic xenograft mouse model using metastatic human Panc-1 cancer cells revealed that pancreatic cancer expresses CCL5 to recruit CD4+Foxp3+ Treg cells, which have high levels of CCR5." (PMID 29379802, 2017). "In addition to induction of IL-10 expression in Foxp3+ Treg cells, TGFβ from CD4+Foxp3+ Treg cells and pancreatic cancer also stimulates transcription factor Foxp3 expression in Foxp3− naïve T cells, leading to differentiation of Foxp3+ Treg cells." (PMID 29379802, 2017). "FOXP3+ lymphocytes accumulation in the lymph nodes may promote tumor cell infiltration into the systemic circulation and accelerate the progression of pancreatic cancer through inhibition of effector T cell function." (PMID 25191901, 2014). "Similarly, there was a trend towards higher density of FOXP3+ lymphocytes in advanced-stage pancreatic cancer than early-stage disease." (PMID 25191901, 2014).
pancreatic cancer (continued). "While levels of FOXP3+ lymphocytes in lymph nodes correlated with the presence or absence of metastases, this was not independently affected by the distance of the lymph nodes from the primary pancreatic cancer." (PMID 25191901, 2014). "In addition, PD-L1 expression and FOXP3+ Treg infiltration also could be prognostic biomarkers for pancreatic cancer." (PMID 33062072, 2020). "Therefore, we tested the hypothesis that elevated levels of FOXP3 immunostaining in primary tumors and regional lymph nodes would predict the presence of lymph node metastases in pancreatic cancer." (PMID 25191901, 2014). "Multifluorescent staining of pancreatic cancer tissues was conducted using antibodies against CD4 (white), CD8 (light blue), CD20 (pink), FOXP3 (red), VIM (green), and panCK (yellow), along with 4',6-diamidino-2-phenylindole, dihydrochloride (DAPI)." (PMID 40303346, 2025). "Cytokines secreted by cancer cells and other stromal cells in pancreatic tumor microenvironment, such as TGF-β1 induce the differentiation of CD4+ CD25- T cells into CD4+ CD25+ Foxp3+ Treg cells." (PMID 37064113, 2023). "Immunohistochemistry staining of pancreatic cancer tissues and adjacent normal tissues was performed using CD3/FOXP3 markers, revealing higher infiltration of T/NK cells and Treg cells in tumor tissues compared to adjacent normal tissues." (PMID 37753069, 2023). "Mouse pancreatic tumor responded to R848 with CD8+ T cells increasing and CD4+CD25+FOXP3+ regulatory T cells decreasing." (PMID 37063284, 2023). "In pancreatic cancer, after neoadjuvant chemotherapy, the median OS of patients with a high CD8+/FOXP3+ lymphocyte ratio was longer than that of patients with a low CD8+/FOXP3+ lymphocyte ratio (p=0.01)." (PMID 34123853, 2021). "In parallel, HO-1 inhibition abrogated the influx of macrophages and FoxP3+ cells, while increasing the proportion of CD8+ infiltration in the pancreatic tumors." (PMID 34066839, 2021). "For example, the depletion of α-SMA+ CAFs in pancreatic cancer accelerates tumor growth, induces immunosuppression by increasing the number of CD4+Foxp3+ Tregs in tumors and reduces survival." (PMID 29545811, 2018). "In pancreatic cancer, variable frequencies of endogenous CD8+ T cells, CD4+Foxp3− T cells, and CD4+Foxp3+ regulatory T cells (Treg) were reported." (PMID 30104497, 2018). "FOXP3, the master transcription factor for regulatory T-cells (Tregs), and its effective cytokine IL10, were also upregulated in the “PDL1-up” group of pancreatic cancers." (PMID 27589570, 2016). "A phase II trial in locally advanced pancreatic cancer patients revealed elevated c-FOXP3+ cell counts in non-responders who received losartan alongside FOLFIRINOX (FFX) and chemoradiation." (PMID 38047300, 2024). "Moreover, depletion of NT5E, ATG5, FOXP3, and IFNG inhibited the colony formation ability of pancreatic cancer cell." (PMID 38395786, 2024). "In fact, some authors, reported that FOXP3 expression in pancreatic cancer tumors can be induced by activation per se, without being linked to an immunosuppressive function." (PMID 37366900, 2023). "Studies have shown that Foxp3 is highly expressed in thyroid carcinoma and pancreatic cancer, while no or weak Foxp3 expression was detected in the normal cells from these tumor cells, suggesting that Foxp3 has tumor-promoting functions." (PMID 35345443, 2022). "A majority of studies revealed that the level of FoxP3+Treg cells had a negative impact on the prognosis of pancreatic cancer." (PMID 34654443, 2021). "In pancreatic cancer patients, a significant negative association was recorded between serum SOCS1 and Foxp3 with the presence of cachexia." (PMID 34900737, 2021). "In addition, in human pancreatic cancer and mouse pancreatic tumor models (Pan02), the CCL5 level on tumor cells is elevated, while CD4+Foxp3– effector T cells preferentially express C‐C chemokine receptor 5 (CCR5)." (PMID 34977871, 2021).
pancreatic cancer (continued). "To determine whether the MDSC and Treg cell interactions are present also in the human pancreatic cancer, we have studied the expression of different immune markers (CD4, CD8, CD15, CD11b, Foxp3) in a cohort of PDAC patients." (PMID 32038621, 2019). "Moreover, it was shown that the expression of cyclo-oxygenase-2 (COX-2) by CAFs in lung or pancreatic cancers leads to their secretion of PGE-2, which plays an essential role in Tregs functionality by inducing FoxP3 expression." (PMID 29545811, 2018). "Foxp3 and CTLA-4 mRNA expression are higher in Tregs from the peripheral blood of patients with progressed and advanced pancreatic cancer, and there should further be a positive correlation between the IL-10 or TGFβ levels and the progression of pancreatic cancer." (PMID 30060755, 2018). "In the setting of pancreatic cancer, it was demonstrated that tumor-infiltrating FOXP3+ cell serves as negative prognostic factor." (PMID 25191901, 2014). "FOXP3+ lymphocyte density did not correlate with age, gender or T stage (including the tumor size and the local infiltration) of pancreatic cancer." (PMID 25191901, 2014). "The density of FOXP3+ lymphocytes was significantly higher in pancreatic cancers with lymph node metastasis compared to those without lymph node metastasis (6.7±5.9/HP vs. 2.3±2.6/HP, p = 0.002)." (PMID 25191901, 2014). "Furthermore, no meta-analysis has been undertaken to evaluate FoxP3+Treg cells as a prognostic marker in pancreatic cancer." (PMID 34654443, 2021). "This meta-analysis indicated that high levels of intratumoral or peritumoral FoxP3+Treg cell infiltration could be recognized as a negative factor in the prognosis of pancreatic cancer." (PMID 34654443, 2021). "Furthermore, we have made the novel observation that FOXP3 expression is higher in lymph nodes containing pancreatic cancer metastases than in those that are negative for carcinoma." (PMID 25191901, 2014). "However, in line with other studies on pancreatic cancer, most CD39+ CD4+ T cells were FOXP3+ CD25+ Tregs and were not correlated with better survival." (PMID 38335302, 2024).
hepatocellular carcinoma (89 papers, 2009 to 2025). A malignant tumor that arises from hepatocytes. "Alternatively, high Foxp3 expression has been associated with better OS in patients with hepatocellular carcinoma based on its capacity to inhibit the expression of the oncogenic protein c-Myc and induce apoptosis in tumor cells." (PMID 35915403, 2022). "Regarding FOXP3 SNP rs2280883 a possible relation between systemic sclerosis in female patients as well as a potential association with hepatitis B-related hepatocellular carcinoma were described." (PMID 32545568, 2020). "Our pooled results showed high density of FoxP3+ Tregs infiltrating was associated with poor survival and high recurrences in hepatocellular cancer." (PMID 26462617, 2015). "A high density of tumor-infiltrating FOXP3 Tregs has been associated with poor outcome in various solid tumors, including ovarian, pancreatic and hepatocellular carcinoma." (PMID 25669968, 2015). "Furthermore, extensive methylation of the FOXP3 promoter region suppresses FOXP3 expression, which has been linked to the progression of hepatocellular carcinoma." (PMID 40244232, 2025). "Moreover, since this study is primarily based on cell lines and mouse models, further investigations are warranted to explore the association between FOXP3 isoforms and subcellular localization in clinical hepatocellular carcinoma tissues." (PMID 40444091, 2025). "In contrast, it has been observed that human breast, ovarian, colorectal, and hepatocellular carcinomas exhibit the recruitment of CXCR3+FOXP3+ Tregs inside the TME." (PMID 38730579, 2024). "Knockdown of macroH2A1, an epigenetic regulatory histone variant, in hepatocellular carcinoma cells promoted chemoresistance and CD4+CD25+FOXP3+ Treg cell activation." (PMID 39232704, 2024). "In this study, we explored the interaction mechanism among HBx, miR-187-5p and transcription factors E2F1 and FoxP3 in hepatocellular carcinoma cells." (PMID 37531206, 2023). "In hepatocellular carcinoma, Foxp3 can suppress tumor progression via TGF-β/Smad2/3 signaling pathway." (PMID 35326661, 2022). "Here, we showed that higher percentage of intratumoral Treg cells was positively correlated with lower Foxp3 promoter methylation in hepatocellular carcinoma (HCC), and both of them were associated with higher tumor grade, larger tumors, and poor prognosis of the patients." (PMID 31006654, 2019). "A positive correlation of Tregs (CD4+ CD25high and the Foxp3 mRNA) with the tumor stage was also noted in patients with hepatocellular carcinoma." (PMID 27866241, 2017). "The high number of FOXP3+ Treg tumour-infiltration in the liver carcinoma microenvironment raises the question of their recruitment." (PMID 27725696, 2016). "This study aimed to evaluate the expression of CD39 and CD39+Foxp3+ regulatory T cells (Tregs) and to determine their prognostic role in patients with hepatocellular carcinoma (HCC) after radical resection." (PMID 27749555, 2016). "Most of the studies looking at hepatocellular cancer reported poor prognostic effect of FoxP3+ Tregs, and the remaining studies reported neutral prognostic claims." (PMID 26462617, 2015). "In particular, a high CD8+/Foxp3+CD4+ T cells ratio has been associated with favorable disease outcome in ovarian and hepatocellular carcinoma patients and with a poor prognosis in subjects affected by head and neck cancer." (PMID 26604855, 2015). "Intra-tumoral accumulation of CXCR3+Foxp3+ T cells has been reported in human ovarian, colorectal, and hepatocellular carcinomas." (PMID 23874342, 2013). "It is further confirmed that the expression of lncRNA-NEAT1 and PKM2 is positively correlated, and there is colocalization between lncRNA-NEAT1 and FOXP3, and lncRNA-NEAT1 promotes the proliferation and metastasis of hepatocellular carcinoma by regulating the FOXP3/PKM2 axis." (PMID 40110044, 2025).